SLC43A2 (solute carrier family 43 member 2)
Diseases named in the same sentence as SLC43A2 in open-access papers (continued):
Sharing a sentence is not in itself a finding about the gene and the disease.
cancer (24 papers, 2015 to 2025). A tumor composed of atypical neoplastic, often pleomorphic cells that invade other tissues. "A study found that cancer cells express high levels of methionine transporter SLC43A2 for the consumption of more methionine, which causes cancer progression." (PMID 37627515, 2023). "Cancer cells often overexpress SLC43A2, limiting methionine availability for T cells, and IDO1 hyperactivation promotes immunosuppression via kynurenine accumulation." (PMID 40475762, 2025). "Numerous studies documented that a variety of cancer cells overexpressed the methionine transporters (e.g., SLC43A2, SLC7A5, and SLC6A14) to uptake and outcompete methionine resource with immune cells." (PMID 41445748, 2025). "Methionine promotes the asymmetric dimethylation of YAP R124 (YAP R124me2a), catalyzed by PRMT1, stimulates the transcriptional activation of SLC43A2, and establishes a positive feedback loop to enhance methionine uptake by cancer cells." (PMID 40430461, 2025). "A study revealed that cancer cells exhibit elevated levels of the Meth transporter SLC43A2, facilitating their increased uptake of Meth, which in turn promotes cancer progression." (PMID 39596358, 2024). "In a novel study, CRISPR/Cas9 system carrying in nanoplatforms was used to decrease methionine intake by cancer cells via inhibiting SLC43A2." (PMID 38705513, 2024). "The genetic ablation of SLC43A2 in cancer cells restores methionine metabolism in CD4 T cells, increasing the intracellular levels of S-adenosylmethionine and yielding H3K79me2." (PMID 37147330, 2023). "The selective upregulation of the methionine transporter SLC43A2 allows cancer cells to outcompete cells in the tumor microenvironment for methionine supply." (PMID 37760083, 2023). "MCR blocked cancer progression via stimulating ferroptosis through the positive feedback loop between SLC43A2 and NFκB signaling pathways." (PMID 37268653, 2023). "Meanwhile, SLC43A2 alters T cell methionine metabolism and histone methylation in cancer." (PMID 38639872, 2024). "SLC43A2 is a major transporter of methionine in several types of cancer cells." (PMID 37147330, 2023). "Cancer SLC43A2 can alter T-cell methionine metabolism and histone methylation." (PMID 36618700, 2022). "In addition, RPTOR (Regulatory Associated Protein Of mTOR Complex 1) has been reported to play a key role in nutrient and insulin-sensing pathways regulating cell growth in cancer, while SLC43A2 has also been identified as a regulator of the mTORC1 complex in cancer studies." (PMID 41373473, 2025). "VIRMA further accelerated the degradation of SLC43A2 mRNA via the m6A-YTHDF2 pathway, reducing phenylalanine uptake and oxidative stress in cancer cells, ultimately leading to cancer progression." (PMID 40723784, 2025). "It has been reported that SLC43A2 and SLC7A5 show increased expression in many types of cancer, and play a critical role in controlling protein translation and cell growth through the mTORC1 pathway." (PMID 28410417, 2017). "As an inhibitor that specifically targets SLC43A2 is not available, suppressing all the L-type amino acid transporters inhibits methionine uptake by both T cells and cancer cells and also inhibits CD8 T ccellinfiltration." (PMID 38705513, 2024). "Cancer cells upregulate multiple amino acid transporters as a means to increase the influx of amino acids from circulation; this includes the transporters SLC7A5 (LAT1), SLC1A5 (ASCT2), SLC6A14 (ATB0,+), SLC7A11 (x-c), SLC38A5 (SNAT5) and SLC43A2." (PMID 36765717, 2023). "SLC43A2 is a Na+-, Cl−-, and pH-independent high affinity transporter of large neutral amino acids whose role in cancer has not been determined." (PMID 26573568, 2015).
cancer (continued). "Two other sodium-independent large amino acid transporters, SLC43A1 and SLC43A2 are also absent, leaving SLC6A15 encoding a known transporter of BCAA found in the mammalian brain, and SLC7A6, an antiporter exporting Arg and Lys in exchange for Leu, Ile and Gln also expressed in brain and cancers." (PMID 37918802, 2023).
inflammation (1 paper, 2024). Aberrant reaction of the microcirculation characterized by movement of fluid and leukocytes from the blood into extravascular tissues. "Common upregulated genes were e.g. important for T cell immunobiology (ARG2, SLC43A2, IGFLR1), involved in cell migration (LAYN) or known to be involved in cigarette smoke-induced pulmonary inflammation and autophagy in mice (EPHX2)." (PMID 39052598, 2024).
SLC43A2 also shares sentences with these, for which no sentence is quoted: prostate carcinoma (2 papers); bladder cancer (1); cardiomyopathy (1); clear cell renal cell carcinoma (1); colon cancer (1); colorectal adenocarcinoma (1); colorectal tumors (1); esophageal cancer (1); glioblastoma (1); Intellectual disability (1); mental disorder (1); panic disorder (1); paraganglioma (1); renal cell carcinoma (1); social anxiety disorder (1); thyroid cancer (1); ulcerative colitis (1).